RUNX2 (RUNX family transcription factor 2)
Diseases named in the same sentence as RUNX2 in open-access papers (continued):
Sharing a sentence is not in itself a finding about the gene and the disease.
lung carcinoma (continued). "Specifically, we detected RUNX2 overexpression in tumor tissue and lung cancer cell lines." (PMID 37754231, 2023). "However, information related to other target genes regulated by the RUNX2 TF in lung cancer is scarce." (PMID 37754231, 2023). "Specifically, RUNX2 is the master transcription factor (TF) of osteoblastic differentiation, and it can be involved in pathological conditions such as prostate, thyroid, and lung cancer by regulating apoptosis and mesenchymal–epithelial transition processes." (PMID 37754231, 2023). "The association of RUNX2 and BRCA1 with the osteoblastic lineage may suggest that its dysregulation in lung cancer may occur in the formation of coregulatory complexes, thereby affecting the function of multiple essential genes in lung pathologies." (PMID 36551878, 2022). "TWIST1 was also deregulated in IPF and PAH; however, it did not appear in any LC-LD CCPs; therefore, the evidence of its association with lung cancer is not as strong as it is for RUNX2." (PMID 36551878, 2022). "By analyzing public databases for recurrent RUNX2 genetic and epigenetic modifications in lung cancer, we found that the most common RUNX2 genetic alteration that exists in transcription upregulation is, followed by genomic amplification, nucleotide substitution and multiple changes." (PMID 31832019, 2019). "In context of Runx2-mediated BMP-3B suppression in mesenchymal cells and to understand the upstream regulatory mechanisms of BMP-3B silencing in lung cancers, we hypothesized that Runx2 downregulates BMP-3B expression in lung cancer." (PMID 22537242, 2012). "Here we show that Runx2 is highly expressed in lung cancer cells and downregulates BMP-3B." (PMID 22537242, 2012). "In addition, we find that the Runx2 overexpression in lung cancer cells results in a significant decline in cell proliferation but enhances wound healing response." (PMID 22537242, 2012). "Furthermore, ectopic expression of Runx2 enhances the migration potential of lung cancer cells in response to the TGFβ signaling." (PMID 22537242, 2012). "Since TALAM1 is a transcriptional target of the RUNX2 TF, its function in lung cancer is likely related to the transcriptional regulation of these genes through their interaction with Polycomb group proteins; however, further studies are required to verify this hypothesis." (PMID 37754231, 2023). "Here, we report that overexpression of the RUNX2 gene in lung cancer may be related to the inhibition of the intrinsic apoptosis pathway, specifically, through direct transcriptional regulation of the antiapoptotic gene BCL2 and indirect regulation of BCL-XL and MCL1." (PMID 36510562, 2022). "Our results help to characterize RUNX2, indicating that it could be a master regulator and direct regulator of many genes and that other TFs are involved in the regulation of gene expression in lung cancer." (PMID 36551878, 2022). "To investigate whether Runx2 suppresses BMP-3B levels in lung cancer cells similar to observed in primary calvarial cells, we stably overexpressed wild type Runx2 (WT) and Runx2 DNA binding domain mutant (DBD) in normal lung fibroblast cells (WI-38 and IMR-90) by lentiviral-mediated gene delivery." (PMID 22537242, 2012). "This relationship provides an understanding of the role of the RUNX2 transcription factor in the lung tumor context and poses new questions about the functional role of the lncRNA TALAM1 in lung cancer that need to be answered." (PMID 37754231, 2023). "Depletion of RUNX2 improves BMP-3b transcription by decreasing the methylation level of the BMP-3b promoter, thereby inhibiting migration and proliferation of lung cancer cell line H1299." (PMID 36429115, 2022). "MiR-196b must be significantly decreased in lung cancer to maintain tumor cell viability, migration, and invasion and EMT induction by TGF-β, PI3K/AKT/GSK3β, Smad, and JNK pathways, as Runx2 is a putative target of miR-196b." (PMID 36551878, 2022).
lung carcinoma (continued). "Collectively, these results indicate that Runx2 downregulates BMP-3B levels in normal lung fibroblast and lung cancer cells." (PMID 22537242, 2012). "Taken together, these studies revealed that the inverse relationship between Runx2 and BMP-3B levels observed in calvarial mesenchymal cells also holds true for normal lung fibroblasts and lung cancer cells." (PMID 22537242, 2012). "Our results show that Runx2 downregulates BMP-3B and increases migration potential of lung cancer cells in response to TGFβ treatment." (PMID 22537242, 2012). "Our studies identify BMP-3B as a Runx2 target gene and show that Runx2 promotes epigenetic silencing of BMP-3B in lung cancer cells by promoting histone H3K9 methylation status of the proximal regulatory regions." (PMID 22537242, 2012). "We show that BMP-3B is a novel Runx2 target gene and find an inverse relationship between Runx2 and BMP-3B expression levels in normal lung fibroblast and lung cancer cells." (PMID 22537242, 2012). "Taken together, our results identified BMP-3B as a new Runx2 target gene and revealed a novel function of Runx2 in epigenetic silencing of BMP-3B in lung cancer cells." (PMID 22537242, 2012). "In contrast to the Runx2 expression levels, BMP-3B mRNA was detectable but lower in lung cancer cells compared to normal lung fibroblast cells." (PMID 22537242, 2012). "Interestingly, Tandon and colleagues demonstrated that there also exists an inverse relationship between RUNX2 and GDF10 expression in lung cancer cells." (PMID 39307303, 2024). "Although the role of RUNX2 in lung cancer has been partially validated, no information on its regulatory targets acquired through bioinformatics or ChIP-seq analysis in lung cancer has been reported." (PMID 37754231, 2023). "The second suggests a cooperative function between RUNX2 and three transcription factors (BRCA1, FOXM1, and RUNX1) important for the specific regulation of lung cancer establishment and progression, along with three transcription factors (E2F3, FHL2, and TWIST1) of the NSCLC-GRN." (PMID 36551878, 2022). "Similarly, RUNX2 is a coregulator of three TFs (E2F3, FHL2, and TWIST1) that also appear in the NSCLC lung cancer regulatory network." (PMID 36551878, 2022). "BMP2 could induce lung cancer migration, invasion, and EMT via activation of MAPK/Runx2/Snail signaling pathway." (PMID 32195173, 2020). "RUNX2 and LEF1 are also targeted by miR-196b and miR-557 inhibiting lung cancer metastasis." (PMID 31027181, 2019). "Taken together, these results show that the recruitment of Runx2 and Suv39h1 on the BMP-3B proximal promoter sequences resulted in increased H3K9 methylation status and consequently downregulation of BMP-3B expression in lung cancer cells." (PMID 22537242, 2012). "The ectopic expression of Runx2, but not DNA binding mutant Runx2, in normal lung fibroblast cells and lung cancer cells resulted in suppression of BMP-3B levels." (PMID 22537242, 2012). "Ectopic expression of DBD mutant of Runx2 failed to downregulate BMP-3B levels in normal lung or lung cancer cells." (PMID 22537242, 2012). "To confirm RUNX2 overexpression in lung cancer, we performed qPCR analysis and immunofluorescence assays in the lung adenocarcinoma cell lines PC9 and A549 and in the tumor tissues obtained from 11 patients, 5 with primary lung cancer and 6 with secondary cancer with lung metastasis." (PMID 37754231, 2023). "Our findings indicate that RUNX2 could be an important regulator of the lung cancer GRN through the formation of coregulatory complexes with other TFs related to the establishment and progression of lung cancer." (PMID 36551878, 2022). "Similarly, in lung cancer, the circRNAs, namely, hsa_circ_0051620| SLC1A5 and hsa_circ_0066954| POLQ, are upregulated and are shown to interact with and regulate driver genes, namely, ADAM17, CDH2, RUNX2, and ZBTB18, through miR-338-3p." (PMID 34055888, 2021).
lung carcinoma (continued). "For example, Runx2 interaction with p300 alters chromatin structure (acetylation of histones H3 and H4) during activation of MMP-13 gene in bone cell lineage in response to PTH and enhances histone acetylation resulting in increased Snail expression and decreased E-cadherin in lung cancer cells." (PMID 22537242, 2012). "However, the transcription regulation of RUNX2 on OPN in lung cancer is still not clear." (PMID 31832019, 2019). "Quantitative gene expression of SPP1, VEGFA, POSTN, RUNX2, CD44, and FOXO1 from lung cancer patients with and without bone metastasis normalized against healthy control." (PMID 36424413, 2022). "RUNX2 also acts as a coregulator of FOXM1, the TF that regulates lung cancer CCPs, and RUNX1, a TF that is coexpressed in the networks of unique lung cancer genes that are not deregulated in other lung diseases (LCI) or other types of cancer (LCII)." (PMID 36551878, 2022). "Moreover, RUNX2 is a coregulator of three of the transcriptional regulators identified in the NSCLC-GRN (i.e., E2F3, FHL2, and TWIST1), suggesting a cooperative function of these TFs in lung cancer, which has not been studied experimentally in lung cancer." (PMID 36551878, 2022). "Similarly, RUNX2 is also a coregulator of RUNX1, a TF of the same family, and is coexpressed in coexpression networks of unique lung cancer DEGs that are not dysregulated in other lung diseases (LCI) or in other types of cancer (LCII), with which it shares binding motifs with its target genes." (PMID 36551878, 2022).
thyroid cancer (23 papers, 2013 to 2024). "RUNX2 overexpression has been described in thyroid carcinomas and has been linked to the EMT process in different types of tumors." (PMID 24069422, 2013). "In thyroid cancer, RUNX2 promotes EMT and tumor invasion by inducing the expression of EMT-related molecules such as SNAI2, SNAI3, TWIST1, and MMP2." (PMID 38430423, 2024). "In thyroid cancer, the biological significance of RUNX2 in follicular thyroid cancer ML-1 cells was investigated." (PMID 37108164, 2023). "In thyroid cancer, a reduction in invasion activity was detected after silencing RUNX2 by siRNA in ML-1 cells." (PMID 37108164, 2023). "RUNX2 protein was elevated in human thyroid cancer cell lines and cancer tissues compared with primary cell lines and normal thyroid tissues." (PMID 37108164, 2023). "In thyroid cancer, RUNX2 acts as an oncogene, mediating aggressive features of tumor and controlling migration and invasiveness." (PMID 35267576, 2022). "In this study, we show that the expression of TRβ1 protein is downregulated in human thyroid cancer tissues and cell lines compared with the normal thyroid tissues and primary cell line, whilst Runx2 is upregulated under the same conditions." (PMID 36497320, 2022). "We downloaded the representative images of TRβ1 and Runx2 protein expression in normal and thyroid cancer patients’ tissues." (PMID 36497320, 2022). "The importance of both TRβ1 and Runx2 has been investigated in several forms of cancer, including breast and thyroid cancer." (PMID 36497320, 2022). "The expression of TRβ1 was downregulated but Runx2 upregulated in all investigated thyroid cancer cell lines compared to normal primary thyroid cells." (PMID 36497320, 2022). "In these DEGs, RUNX2 was positively correlated with IGF2BP2 and negatively associated with NIS in thyroid cancer." (PMID 35267576, 2022). "We show here that the expression of the nuclear transcription factors TRβ1 and Runx2 is regulated by calcium in thyroid cancer cells." (PMID 36497320, 2022). "The expression of the TRβ1 gene was significantly down-regulated, while the Runx2 gene was significantly up-regulated in both the papillary and combined thyroid cancer tissues (Total), compared to respective tumor adjacent normal thyroid tissues (NT)." (PMID 36497320, 2022). "In thyroid carcinoma, abolishing the expression of RUNX2 suppresses the expression of EMT and angiogenesis-related factors." (PMID 36429115, 2022). "In previous studies, we identified RUNX2 as a stemness marker for cancer and observed higher levels of RUNX2 expression in thyroid cancer patients with bone metastases." (PMID 32204402, 2020). "Runx2 increases the secretion of various MMPs to promote metastatic ability in thyroid cancer cells." (PMID 33086487, 2020). "In thyroid carcinomas, Runx2 was upregulated in follicular cell-derived thyroid carcinomas and contributes to invasion and metastatic ability by regulating angiogenic/lymphangiogenic factors and epithelial mesenchymal transition (EMT)-related molecules." (PMID 33086487, 2020). "Being tubacin a HDAC6 specific inhibitor, these data indicate that HDAC6 is selectively involved in RUNX2 transcription in this thyroid cancer cell line, highlighting a close connection between proliferation inhibition and RUNX2 down-regulation." (PMID 31395086, 2019). "Here, to fill this gap, we investigated the role of different HDACs in RUNX2 expression regulation in breast and thyroid cancer, tumors that majorly rely on RUNX2 for their development and progression." (PMID 31395086, 2019). "We previously reported that treatment with HDACi profoundly impairs RUNX2 expression in thyroid cancer." (PMID 31395086, 2019). "The TRβ1 and Runx2 genes expression datasets (low and high) available for all thyroid cancer types and stages (I–IV) were downloaded from The Cancer Genome Atlas (TCGA), followed by the survival curve analyses based on Kaplan-Meier estimates to calculate the survival probability of the patients." (PMID 36497320, 2022).
thyroid cancer (continued). "Expression levels of TRβ1 and Runx2 genes were compared between thyroid tumor tissues (n = 502) and normal tumor-adjacent or para-cancerous thyroid tissues (n = 58) using RNA sequencing data from the TCGA Thyroid Carcinoma cohort." (PMID 36497320, 2022). "Runx2 was also demonstrated to be involved in the regulation of EMT in thyroid carcinomas." (PMID 33086487, 2020). "Besides Runx-2 upregulation in PTC and in thyroid carcinoma cell lines, the authors reported its association with the mitogen-activated protein kinase kinase/extracellular signal-regulated kinase (MAPK/ERK) pathway." (PMID 33086487, 2020). "Furthermore, we found an additional and cell-specific function of HDAC6 in driving RUNX2 expression in thyroid cancer cells." (PMID 31395086, 2019). "Recent studies have suggested that molecules such as thyroid hormone receptor beta (THRβ) and Runt Related Transcription Factor 2 (RUNX2) may be involved in the mechanism responsible for calcification in thyroid cancer." (PMID 30049993, 2018). "In addition, hsa-mir-375 was inferred to be significant for patients’ survival with 34 associated ceRNAs, among which RUNX2, DUSP6 and SEMA3D are known oncogenes regulating cellular proliferation and differentiation in thyroid cancer." (PMID 29351231, 2018). "Similarly, RUNX2 silencing in human thyroid cancer cell lines results in decreased mRNA expression of SNAI2 and invasion." (PMID 26204939, 2015). "If this hypothesis is correct blocking the TGF-β signaling in thyroid cancer cells should affect RUNX2 and CDH6 expression levels." (PMID 24069422, 2013). "Furthermore, we wanted to investigate whether modulating TRβ1or Runx2 expression affected the phenotype of the thyroid cancer cells." (PMID 36497320, 2022). "Moreover, Runx2 has also been shown to have oncogenic properties, and an up-regulation of Runx2 has been correlated with a worsened prognosis of several cancers, including thyroid cancer." (PMID 36497320, 2022). "Thus, we explored whether HDAC6 assists RUNX2 in the regulation of specific target genes in thyroid cancer, beside their cooperation in controlling RUNX2 expression." (PMID 31395086, 2019). "In thyroid cancer cells, HDAC6 potentiates RUNX2 transcription, stabilizing the assembly of the transcriptional complex on the RUNX2 P2 promoter." (PMID 36551878, 2022). "Runx2 has also been found to be highly expressed in BHP-cultured papillary carcinoma cells and surgically excised human thyroid cancer tissues." (PMID 35163879, 2022). "Since a functional interplay between RUNX2 and HDAC6 has been suggested, we used RNA-Seq profiling to consolidate this evidence in thyroid cancer and to extend the knowledge on this cooperation in a setting in which HDAC6 also controls RUNX2 expression." (PMID 31395086, 2019). "To further elucidate the functional interplay between RUNX2 and HDAC6, we sought to investigate the transcriptional program of the RUNX2- HDAC6 complex, in thyroid cancer cells." (PMID 31395086, 2019). "RUNX2 also participates in TGF-β signal pathway and in TGF-β-induced EMT, as RUNX2 is upregulated in TGF-β1-treated thyroid carcinomas cells." (PMID 28978036, 2017). "We recently showed that TGFβ treatment in normal and thyroid cancer cell lines induces EMT through the activation of RUNX2 and its target CDH6.55, 56, 57 CDH6 silencing reverts the EMT phenotype and restrains migration and invasiveness in thyroid cancer cells." (PMID 27929542, 2016). "RUNX2, a mammalian RUNT-related transcription factor, is increasingly recognized in cancer biology for its role in supporting survival and progression also in thyroid cancer (TC)." (PMID 39271656, 2024). "i) Correlation of RUNX2 and HDAC6 expression in thyroid cancer samples from TCGA database." (PMID 31395086, 2019).
thyroid cancer (continued). "siRNA-mediated RUNX2 depletion impaired the positive transcriptional TGFβ effect on the expression of cadherin 6 (CDH6), whose product is a potential mesenchymal marker of the EMT program in thyroid cancer, controlling invasiveness of thyroid tumors." (PMID 26204939, 2015). "In thyroid cancer cells, HDAC6 could stabilize the transcriptional complex of RUNX2." (PMID 36429115, 2022).